INS (insulin)
Diseases named in the same sentence as INS in open-access papers (continued):
Sharing a sentence is not in itself a finding about the gene and the disease.
Insulin resistance (continued). "Chemerin down-regulates insulin signalling, induces insulin resistance, inhibits insulin receptor substrate 1 and glycogen synthase kinase phosphorylation, and impairs glucose uptake in skeletal muscle." (PMID 38139115, 2023). "TNF induces insulin resistance in adipocytes by inhibiting insulin-induced IRS1 tyrosine phosphorylation and insulin-induced glucose uptake." (PMID 36818229, 2023). "Insulin resistance develops before insulin hypersecretion, which is viewed as a step to meet high insulin requirements." (PMID 37241737, 2023). "The key mechanism of insulin resistance is dysfunction of the insulin signaling, while the IRS1/AKT/FOXO1 signaling pathway plays a vital role." (PMID 38034083, 2023). "Insulin resistance is referred to as decreased insulin sensitivity, which compromises insulin-induced glucose uptake in muscle and adipose tissue and hepatic gluconeogenesis." (PMID 37895834, 2023). "DGAT1 overexpression in skeletal muscles protected mice from high fat diet-induced insulin resistance, while DGAT1 deficiency diminished insulin sensitivity." (PMID 37684349, 2023). "This class of medicines has the potential to increase insulin sensitivity and reduce insulin resistance." (PMID 37047011, 2023). "T2D occurs when early insulin secretion decreases, and the pancreas is unable to overcome insulin resistance." (PMID 37049602, 2023). "Hepatic insulin resistance, characterized by impaired insulin-mediated suppression of glucose output from the liver, contributes to increased blood glucose levels." (PMID 37614321, 2023). "It has been shown that polymorphisms in the PPARG gene are involved in the development of both insulin resistance and impaired insulin secretion by pancreatic beta-cells." (PMID 36902173, 2023). "Though there is a correlation between insulin resistance and increased ET-1 activity, insulin can inhibit ET-1 release from mouse microvascular endothelial cells." (PMID 37893034, 2023). "Adipose tissue insulin resistance precedes muscle insulin resistance during high-fat feeding, and adipose-specific abrogation of insulin action leads to systemic insulin resistance." (PMID 36808134, 2023). "High doses of glucocorticoid have an oppositional effect on insulin, reducing the sensitivity of insulin (i.e., increasing insulin resistance), reducing beta cell mass, and reducing insulin synthesis, which can lead to hyperglycemia." (PMID 36676776, 2023). "Glucose hypometabolism, systemic insulin resistance (IR), and insulin signaling abnormalities in neuronal cells have been implicated in the pathophysiology of major psychiatric disorders." (PMID 36302978, 2023). "The enhanced basal insulin secretion drives insulin resistance and β-cell exhaustion and thus the onset of T2DM in mice fed an HFD or with gain-of-function BRSK2 in β cells." (PMID 37188647, 2023). "The cytokines found to hinder the function of insulin, which is crucial in regulating blood sugar levels, have been demonstrated to promote insulin resistance, a defining characteristic of T2D." (PMID 37600709, 2023). "Another significant source of ROS generation in β-cells is the increasing demand for insulin, as occurs in conditions of insulin resistance, which leads to elevated synthesis of this hormone." (PMID 37237860, 2023). "A chronic metabolic disorder called diabetes mellitus is characterised by persistently high blood glucose levels, insulin resistance, and insufficient amounts of insulin compared to physiological requirements." (PMID 38024367, 2023). "Insulin therapy is ultimately needed for most patients, and metformin should be considered when concomitant insulin resistance is present." (PMID 36979645, 2023). "A primary characteristic of insulin resistance is decreased recruitment of GLUT4 to the cell surface in response to insulin due to impaired GLUT4 trafficking, as recently reviewed." (PMID 38292764, 2023).
Insulin resistance (continued). "PCOS women can decrease insulin resistance by losing weight (if obese) or using insulin-sensitizing agents." (PMID 36676074, 2023). "The synthesis of large amounts of oxygen free radicals can cause lipid peroxidation damage to ovarian tissues and insulin pancreatic islet β cells, which can cause PCOS and its insulin resistance." (PMID 37701184, 2023). "The decrease in insulin resistance was characterized by low serum insulin levels in treatment groups." (PMID 37483646, 2023). "This is associated with improved serum insulin, HOMA-IR measure of insulin resistance, and whole-body insulin sensitivity." (PMID 36586437, 2023). "Various mechanisms have been proposed to link HbA1c with the development of atherosclerosis, including through insulin resistance due to endothelial dysfunction and an abnormal insulin vasodilative effect mediated by endothelium‐derived nitric oxide." (PMID 37329140, 2023). "One of the main pathophysiological mechanisms of metabolic syndrome is insulin resistance, which results in hyperinsulinemia, and insulin has been shown to increase the expression of URAT1 in kidney epithelial cells." (PMID 37694143, 2023). "Here researchers use co-culture of hepatocytes and macrophages derived from the same human iPSC line to show how inflammation disrupts insulin-mediated regulation of hepatic glucose metabolism and identify targets for therapy of hepatic insulin resistance." (PMID 37400454, 2023). "Berberine is known to act mainly by mimicking the action of insulin, reducing insulin resistance, and upregulating the expression of insulin receptors." (PMID 37111281, 2023). "Type 2 diabetes is characterized by progressive hyperglycemia due to impaired insulin secretion or/and insulin resistance." (PMID 37324170, 2023). "Heightened systemic inflammation typical of untreated HIV is known to disrupt insulin signaling at end organs including skeletal muscle, adipocytes and the liver leading to insulin resistance as well as impaired insulin production." (PMID 37577475, 2023). "Because insulin-mediated effects on immune cells, including insulin resistance, can drive both pro- and anti-inflammatory effects, we will also discuss proposed mechanisms behind insulin’s pleiotropic effects and highlight their implications in disease." (PMID 36992811, 2023). "Insulin resistance and reduced insulin levels are known to correlate with protein breakdown, while increased insulin levels stimulate protein synthesis." (PMID 36978832, 2023). "Insulin resistance, a condition where insulin secretion is diminished or insulin is unable to efficiently facilitate the transportation of glucose into the body’s peripheral tissues, is crucial in the development of both MetS and T2DM." (PMID 38049837, 2023). "A switch from boosted PIs (DRV, ATV, and LPV) to INSTIs (RAL and DTG) regimens has shown an improvement in insulin sensitivity, reduction of insulin (and homeostatic model assessment—insulin resistance (HOMA-IR)) and leptin levels." (PMID 38140673, 2023). "Together with the elevated glucose levels, this led to an increased HOMA index (directly depending on serum glucose and insulin levels under fasting conditions), which indicated a state of insulin resistance in KO mice after HFD feeding." (PMID 36766785, 2023). "One such novel prediction is CD74 for insulin—this gene’s role in insulin secretion and related diseases was not well-established until the recent discovery of its participation in insulin resistance." (PMID 37093889, 2023). "In T2D, chronic insulin resistance eventually overwhelms pancreatic insulin production and culminates in beta cell failure." (PMID 37759961, 2023). "The metabolic pathway of insulin resistance leads from insulin to glucose transporter type 4 (GLUT4), which regulates glucose uptake." (PMID 38003403, 2023). "Insulin resistance is important pathogenesis of T2DM in which the insulin signaling pathway plays a central role." (PMID 37786444, 2023).
Insulin resistance (continued). "Irg1−/− mice on WD also had insulin resistance as well as significantly elevated blood insulin levels." (PMID 37308721, 2023). "The main site affected by gestational insulin resistance is skeletal muscle, which considerably reduces its sensitivity to insulin in the second half of pregnancy." (PMID 37765126, 2023). "Selective insulin resistance is also associated with DNL activation induced by SREBP1c, which allows insulin to sustain the elevated DNL level." (PMID 38089874, 2023). "Changes of BVRA significantly correlate with indexes of increased insulin resistance and insulin secretion (HOMA-IR, HOMA-β, and insulinogenic index)." (PMID 37108445, 2023). "Of the non-insulin-based formulas, we have selected those that have shown a better correlation with insulin resistance." (PMID 37432258, 2023). "Brain insulin resistance and low levels of brain insulin often lead to metabolic and cognitive dysfunctions, including obesity, type 2 diabetes, and Alzheimer’s disease." (PMID 37886966, 2023). "Pioglitazone decreases insulin resistance in the peripheral muscle and liver, resulting in increased insulin-dependent glucose disposal and decreased hepatic glucose output, respectively." (PMID 38004396, 2023). "This study highlighted the amelioration of fasting plasma insulin and insulin resistance in children with hyperinsulinemia." (PMID 37761441, 2023). "Women have a plasma level of 25(OH)D and it is inversely correlated with serum insulin, insulin resistance, total cholesterol, LDL-C, and HDL-C." (PMID 37239168, 2023). "Insulin secretion and insulin resistance, two crucial processes connected to type 2 diabetes, are dependent on vitamin D levels." (PMID 37107924, 2023). "Insulin resistance is a prominent feature of T2D, and skeletal muscle is an important site of insulin-mediated glucose uptake." (PMID 37511225, 2023). "Very interestingly, it has been found to reverse insulin resistance also by inhibiting hepatic glucose output and enhancing insulin signaling in the liver and skeletal muscle." (PMID 37189744, 2023). "We previously reported an increase in insulin resistance via insulin tolerance test in the mTORKOpl female adult offspring under metabolic stress by HFD-induced obesity." (PMID 37855320, 2023). "The cytokine impairs glucose and insulin metabolism in young diabetic mice and increases the production of IL-6, which induces insulin resistance." (PMID 36768715, 2023). "TNF-α and IL-6 indirectly inhibit the activation of insulin signaling and sustaining insulin resistance." (PMID 36767041, 2023). "Pathogenesis of T2DM is fueled by inducing insulin resistance in skeletal muscle, liver, and fat so that insulin signaling is disturbed." (PMID 37441501, 2023). "In contrast, adiponectin, an anti-inflammatory adipokine, decreased in obesity, acts as an insulin-sensitizing hormone in muscles and the liver; low levels of adiponectin contribute to peripheral insulin resistance." (PMID 36986134, 2023). "This has been shown in some studies, where people after cholecystectomy have an increase in fat levels, apolipoprotein B, insulin and in the Homeostatic Model Assessment for Insulin Resistance (HOMA-IR) index." (PMID 37761319, 2023). "Prolonged insulin exposure induced insulin resistance in primary human skeletal muscle-derived cells (HMDCs), as characterized by blunted IRS-1 phosphorylation (Tyr612) and Akt (Ser473) phosphorylation in response to an acute insulin stimulation." (PMID 36942499, 2023). "Insulin resistance broadly refers to a reduced metabolic response to insulin, which, at a systemic level, leads to a diminished lowering of blood glucose for the same amount of circulating insulin." (PMID 37745252, 2023). "Insulin resistance (IR) and impaired insulin secretion are hallmarks of type 2 diabetes mellitus (T2D) and are common in older adults with multiple long-term conditions." (PMID 37898813, 2023).
Insulin resistance (continued). "Insulin resistance is defined as a condition in which peripheral tissues are less sensitive to insulin activity." (PMID 36902406, 2023). "Pregnancy is characterized by a decrease in insulin sensitivity, otherwise called insulin resistance which is the decreased biological response to insulin." (PMID 37650554, 2023). "The expressions of FAS, ACC, and LPL genes were significantly reduced, and body weight gain, serum glucose, insulin levels, and insulin resistance were also significantly inhibited by 6-gingerol." (PMID 37050926, 2023). "Skeletal muscles are quantitatively the largest glucose users in response to insulin and are considered as the main effectors for the development of insulin resistance." (PMID 37178918, 2023). "One of the key mechanisms underlying vascular insulin resistance is impaired signaling of the insulin receptor substrate 1 (IRS-1) pathway, which is a critical mediator of insulin signaling in the blood vessels." (PMID 37610001, 2023). "Lowering dietary carbohydrate intake has demonstrated benefits for insulin resistance, the underlying cause of T2DM, by independently promoting both weight loss and a reduction in insulin levels." (PMID 37998439, 2023). "Whereas skeletal muscle and liver are the main sites of insulin signalling, these tissues can be understood as key to the occurrence of insulin resistance." (PMID 37089923, 2023). "Adiponectin acts as an endogenous insulin sensitizer in the regulation of insulin sensitivity, and its level is inversely correlated with obesity and insulin resistance." (PMID 38149100, 2023). "To further unravel the mechanism through which MELNs mitigate disease progression in T2DM mice, we generated an insulin-resistant hepatocyte model using Glucosamine (GlcN), a substance extensively utilized to simulate insulin resistance in cellular models." (PMID 37759297, 2023). "While these are arbitrary, a plasma insulin concentration of 3000 pmol/L is usually seen only in syndromes of extreme insulin resistance." (PMID 37562398, 2023). "GLP-1 receptor agonists have been shown to enhance insulin sensitivity in both peripheral tissues and the central nervous system, potentially mitigating the detrimental effects of insulin resistance on brain function." (PMID 38002034, 2023). "Biochemically, the HC group had higher HDL cholesterol levels but lower insulin and insulin resistance indices." (PMID 38139760, 2023). "In the obese state, adipocyte hypertrophy increases the production of pro-inflammatory adipokines, leading to adipocyte-derived inflammation, which, in turn, inhibits insulin signaling and eventually leads to insulin resistance." (PMID 37571394, 2023). "The decreased levels of GLUT4 suggest a disruption in the normal insulin-mediated glucose transport process, potentially contributing to insulin resistance and impaired glucose homeostasis." (PMID 37570835, 2023). "Studies have shown that OVX mice fed a high-fat diet (HFD) showed an increase in body weight, fat mass, fasting glycemia and insulin, insulin resistance, and glucose intolerance, in addition to an increase in plasma TAG, hepatic steatosis, and fibrosis." (PMID 37372993, 2023). "AMPK diminished in Psammomys obesus with insulin resistance and type 2 diabetes, possibly due to disruptions in insulin signaling at the jejunum." (PMID 36986224, 2023). "Biochemical assessment showed some differences between groups; as anticipated, women with GDM had higher concentrations of glucose and insulin than euglycemic women, with evidence of insulin resistance." (PMID 36950879, 2023). "Supporting this, our analyses showed that muscle GR can enhance insulin secretion in response to CORT before the induction of insulin resistance." (PMID 36917179, 2023). "The first event in the sequence of processes leading to T2D is insulin resistance, which leads to increased insulin synthesis and secretion and compensatory hyperinsulinemia." (PMID 37873836, 2023).
Insulin resistance (continued). "In the present study, in prehypertensive subjects, when compared to subjects on placebo, fasting insulin levels and insulin resistance are reduced when treated with water-soluble vitamins." (PMID 36751256, 2023). "Although chronic insulin exposure was most commonly used previously in in vitro insulin resistance studies, most in vitro insulin resistance models now utilize FFA exposure, especially palmitic acid exposure." (PMID 36714242, 2023). "Then, we performed in vivo IPITT and GSIS assays, and the results showed that insulin resistance was decreased in the oe-circGlis3-treated Leprdb/db mice and that oe-circGlis3 treatment enhanced insulin secretion." (PMID 36681689, 2023). "Develop estimation models for measures of insulin resistance, including insulin sensitivity index (SI) and homeostatic model assessment of insulin resistance (HOMA-IR) from metabolomics data." (PMID 37558891, 2023). "Obesity is the most common etiological factor in T2D but is not an absolute requirement, with the key pathophysiological features being impaired insulin secretion and/or decreased insulin sensitivity (insulin resistance)." (PMID 37367868, 2023). "Polycystic ovarian syndrome is connected with insulin resistance, which means that when this syndrome is suspected, the parameters of insulin metabolism should be tested." (PMID 37510883, 2023). "We also acknowledge that HOMA-IR and -B were designed and validated to study insulin sensitivity and β cell function in humans, despite this limitation they are commonly used to compare insulin resistance and β cell function in murine models of T2DM." (PMID 37731032, 2023). "Anti-inflammatory treatments can improve insulin sensitivity and β cell function in patients with insulin resistance or T2DM." (PMID 36936906, 2023). "Insulin resistance refers to the impaired response of target tissues, including adipose, liver, and skeletal muscle, to the actions of insulin, leading to diminished glucose uptake." (PMID 37978556, 2023). "The main component affecting the increase in insulin resistance was the increase in insulin concentration in the analyzed period, which was shown in our former work." (PMID 37238721, 2023). "This, in turn, leads to a series of liver dysfunctions, such as reduced hepatic insulin extraction, increased hepatic glucose production, and ultimately results in type 2 diabetes and insulin resistance." (PMID 37794517, 2023). "The reduction of ß-oxidation impairs insulin signaling, leading to ectopic lipid accumulation and the induction of insulin resistance." (PMID 37834407, 2023). "Prospective studies have shown different methylation profiles of interested genes in patients with insulin resistance and variable insulin and glucose blood concentrations." (PMID 37512517, 2023). "Insulin resistance (IR) affects the downstream signaling pathways of insulin, favoring the MAPK pathway over the Pi3K- Akt pathway, thus leading to a number of undesirable metabolic effects such as diabetes, hypertension, and CVD." (PMID 36788883, 2023). "Elucidation of these mechanisms will provide opportunity for prevention and possible use of novel tissue-specific insulin-sensitizing agents that prevent development of insulin resistance in these patients." (PMID 36763576, 2023). "Phenylalanine stimulates insulin secretion and further regulates compensatory mechanisms in the early stages of insulin resistance." (PMID 37393287, 2023). "Type 2 diabetes is characterized by insulin resistance, a diminished response to insulin of cells in the muscles, liver and fat." (PMID 37325174, 2023).